FGFR1 (fibroblast growth factor receptor 1)
Diseases named in the same sentence as FGFR1 in open-access papers (continued):
Sharing a sentence is not in itself a finding about the gene and the disease.
tumor (continued). "Preclinical data have demonstrated that the FGF/FGFR1 axis is a key mediator of angiogenesis and PCa dissemination, whereas targeting this pathway inhibited both tumor growth and blood vessel formation." (PMID 31963871, 2020). "We further found that AGAP2-AS1 exerted its tumor-promoting function through response to miR-497 and regulation of FGFR1." (PMID 32202509, 2020). "The transcriptional coactivator YAP, together with the transcription factor TBX5, has been shown to regulate FGFR1 expression in other tumor types." (PMID 31963871, 2020). "For example, the initial copy number was about 4 for FGFR1 at 80% tumor purity, whilst the copy number was approximately 2.45 at 20% tumor purity." (PMID 32621174, 2020). "We demonstrated that not only BGJ398 and FIIN-2, but also UPR1376 completely inhibited the growth of tumor spheroids generated from H1581 cells, confirming its efficacy as an inhibitor of FGFR1-dependent cell growth." (PMID 30972293, 2019). "We subsequently performed a profiling study on the proliferation, invasion, migration, and EMT of FGFR1-amplified cell lines, which confirmed the tumor-suppressive effect of miR-214-3p." (PMID 31492847, 2019). "Previous studies have indicated that other miRNAs, such as miR-133b, which is another tumor suppressor, also targets FGFR1 to suppress GC." (PMID 31138759, 2019). "Fibroblast growth factor receptor 1 (FGFR1) is an oncogene that can promote tumor cell progression and tumorigenesis through different mechanisms in several cancers, including NSCLC." (PMID 31815619, 2019). "A previous study showed that silencing FGFR1 expression using small interfering RNA was effective in elevating FGFR3 expression and tumor supportive activity, suggesting that FGFR1 and FGFR3 have an inverse relationship." (PMID 31369573, 2019). "Only one target (FGFR1) was found “unchanged”, since dissimilar expression was observed in only one of the 34 paired tumor tissue samples." (PMID 30894200, 2019). "Somatic mutations in the genes encoding VEGFR2, FGFR1, FGFR2, FGFR3, and KRAS were identified in the patient's tumor tissue." (PMID 30792968, 2019). "FGFR1 amplifications are present in several tumour types including squamous non-small cell lung (10%-20%), hormone positive breast (10%), head and neck (10%-17%), squamous oesophageal (20%) and ovarian cancer (9%)." (PMID 35582593, 2019). "MicroRNA (miRNA) and fibroblast growth factor receptor 1 (FGFR1) dysregulation are considered to play an important role in tumor proliferation, invasion, and metastasis." (PMID 31492847, 2019). "Staining for FGFR1–4 was performed in tumor tissue from 94 MPM patients and evaluated using a three-tier semi quantitative scoring system." (PMID 31527449, 2019). "These corroborated that FGFR1 overexpression antagonizes the tumor-suppressive effect of miR-198 and FGFR1 is a target of miR-198." (PMID 31138759, 2019). "Using immunohistochemistry analysis, these findings were recapitulated in NSCLC PDX tumor tissues with FGFR1/2 amplification versus RTK wildtype tumors." (PMID 31221965, 2019). "Our TMA results revealed increased FGFR1 expression in malignant tumors in comparison to benign tumors." (PMID 30931252, 2019). "Abnormal FGFR1 alternative splicing is correlated with tumorigenicity and poor prognosis in several tumor types." (PMID 30713601, 2019). "Mechanistically, western blot analysis of tumor tissues revealed that 15c attenuated H1975 xenograft tumor growth in vivo by suppressing the phosphorylation of FGFR1 and EGFR." (PMID 31998131, 2019). "Poor prognosis of patients with FGFR1-overexpressing tumours subjected to adjuvant tamoxifen-based therapy verified results of experimental studies." (PMID 31142340, 2019). "Collectively, these data indicate that FGF2 secreted by ASCs acts in a paracrine fashion on FGFR1-expressing chemo-residual TNBC cells to activate ERK signaling, which is associated with an increase in tumor cell proliferation." (PMID 30594967, 2019).
tumor (continued). "For example, in a small size cohort study, high FGFR4 expression correlated with tumor progression and survival in both diffuse and intestinal GC, whereas high expression of FGFR1 and 2 correlated with tumor progression and survival only in diffuse type GC." (PMID 31242658, 2019). "Statistical analysis of the protein expression indicated that in tumor-adjacent stroma FGFR1 and MYPT1 were significantly correlated with patient outcomes and LDHB showed the outcome-association tendency." (PMID 31316912, 2019). "First, TCGA covered both FGFR1 gene amplification and mRNA overexpression in primary tumors, whereas our analysis was limited to gene amplification in plasma tumor DNA using a less sensitive NGS assay." (PMID 30914635, 2019). "Patients were segregated into a high expression group and a low expression group according to the fold-change of FGFR1 in tumor tissue to normal tissue more than 2-fold." (PMID 30484492, 2018). "Overexpression of FGFR1 reversed miR-497 mimics inducing growth inhibition and apoptosis, as well as the expression levels of FGFR1 and miR-497 were inversely correlated in the tumor tissues." (PMID 30484492, 2018). "While there was insufficient DNA to quantify DNA methylation before treatment in these patients, FGFR1 gene expression increases after treatment in four of the six tumor samples." (PMID 29792227, 2018). "Group 2 tumours, with approximately half of the tumours displaying a DNET-like appearance, are enriched for FGFR1 mutations." (PMID 29058119, 2018). "Amplification of the Fibroblast Growth Factor Receptor 1 (FGFR1) gene in OS tumour cell lines has previously been shown to predict enhanced sensitivity to FGFR inhibition by the pan-FGFR inhibitor NVP-BGJ39810." (PMID 30006631, 2018). "By targeting FGFR1, miR-133b became a pleiotropic tumor suppressor miRNA, inhibiting the tumorigenic as well as metastatic behaviors of OS cells." (PMID 30574019, 2018). "The purpose of this study is to examine the roles of FGFR1 signaling in gene expression, cell proliferation, tumor growth and progression in a non-invasive DCIS model." (PMID 30111373, 2018). "The need to standardize the methods employed to define amplification of FGFR1 in different tumor types have been noted." (PMID 29351293, 2018). "Here, we have described three distinct mechanisms by which N-cadherin endows tumour cells with increased migratory capacity: facilitation of collective cell migration, augmentation of FGFR-1 signalling and modulation of canonical Wnt signalling." (PMID 30285678, 2018). "In discovery cohort 1, FGFR1 and Klotho beta (KLB) overexpression was associated with low tumor stage (P < 0.05), low tumor grade (P < 0.05), and better overall survival." (PMID 30593273, 2018). "Our results demonstrate that EMT features of tumor cells can be abolished by inhibiting FGFR1 signaling by short interfering (si)RNA or small-molecule kinase inhibitors." (PMID 30326563, 2018). "BGJ398 is an orally available selective inhibitor of FGFR1, FGFR2, and FGFR3 that has been shown to potently inhibit tumor cell proliferation and tumor growth in various cancer models harboring genetic alterations in FGFR1/2/3." (PMID 30326563, 2018). "The immunohistochemical staining analysis also showed a significant increase in the levels of FGFR1 in tumor tissues compared with normal tissues." (PMID 30484492, 2018). "Unexpectedly, additional deletion of endothelial Fgfr1 and Fgfr2 in Vegfr2 heterozygous mice shows similar tumor growth and angiogenesis as the Vegfr2 heterozygous mice." (PMID 30283071, 2018). "MicroRNA-133b (miR-133b), through directly targeting the fibroblast growth factor receptor 1 (FGFR1), is increasingly recognized as a tumor suppressor in different types of cancers." (PMID 30574019, 2018). "Intriguingly, recurrent tumor tissues revealed elevated levels of activated EGFR compensating for FGFR1 inhibition." (PMID 28775339, 2017).
tumor (continued). "High FGFR4 expression correlated with tumor progression and survival in both types of GC, although FGFR1 and 2 correlated with these variables in only DGC." (PMID 28056982, 2017). "In the CNV analysis of individual genes, the copy number state of the CDKN2a, MLH1, and FGFR1 genes is identical in the primary tumour and the cell lines." (PMID 28304377, 2017). "As a tumor suppressor, miR-361-5p inhibited BC cells aerobic glycolysis and proliferation by directly targeting FGFR1, a promoter of glycolytic pathway." (PMID 29132384, 2017). "This is also the first report of anti-tumor activity of a FGFR TKI in a PDECX model with high FGFR1 expression." (PMID 28881608, 2017). "FGFR1 amplification is a common feature of several tumour types and activates the cell cycle via the RAS pathway." (PMID 28304377, 2017). "Other pre-clinical studies on xenograft models transplanted with transformed cells derived from FGFR1 amplified NSCLC cancer patients have shown that AZD4547 stops tumor growth and promotes regression." (PMID 28030802, 2017). "We studied 80 primary and 12 metastatic ccRCC tumors and identified 7 peptide substrates with significantly increased tyrosine phosphorylation by metastatic samples relative to primary tumor samples including FGFR1, FAK1, ACHD, K2C8, EGFR, EPHB4 and MBP." (PMID 28418903, 2017). "Finally, the anti-tumor potency associated with down-regulation of GLUT-1 by FGFR1 and AKT/mTOR co-targeted inhibition was confirmed also in vivo, further strengthening the contention that tackling on cancer glucose metabolism may offer a new therapeutic option for the treatment of SQCLC." (PMID 29190880, 2017). "The third mechanism is that targeting MET kinase leads to the activation of FGFR1 that promotes tumor proliferation and metastatic growth in bone." (PMID 29088840, 2017). "In conclusion, high FGFR4 expression correlated with tumor progression and survival in both DGC and IGC, whereas high expression of FGFR1 and 2 correlated with tumor progression and survival in only DGC." (PMID 28056982, 2017). "We previously reported the relations of the immunohistochemical expressions of FGFR1–4 to tumor progression or poor survival in GC." (PMID 28056982, 2017). "The peptide with the highest phosphorylation by metastatic tumor lysates is derived from FGF receptor (FGFR)-1 with the phosphorylation site corresponding to tyrosine residue 766 (Y766)." (PMID 28418903, 2017). "FGFR1 high amplification (FGFR1high) was defined by an FGFR1/centromere 8 ratio of ≥ 2.0, or average number of FGFR1 signals/tumor cell nucleus ≥ 6.0, or percentage of tumor cells containing ≥ 15 FGFR1 signals, or large cluster in ≥ 10% of cancer cells." (PMID 29088806, 2017). "FGFR1 gene copy number was determined in microarrayed tumor samples using fluorescent in situ hybridization (FISH) analysis." (PMID 29179482, 2017). "In conclusion, ponatinib exhibits anti-tumor efficacy in NB by inhibiting FGFR1 signaling and blocking the activation of PI3K/AKT/mTOR and JAK/STAT3 signaling pathways, as evidenced by both in vitro and in vivo assays." (PMID 27564113, 2017). "In tumor cells, oncogenic forms of fibroblast growth factor receptor type 1 (FGFR1) have been shown to inhibit the PKM2 isoform’s activity through a direct phosphorylation of PKM2 tyrosine residue 10536." (PMID 27883057, 2016). "Of note, an additional 72-year old male with a T4N1Mx small intestine GIST possessed a FGF6 amplification, among multiple other GAs, potentially having the same functional impact on tumor growth since FGF6 is a reported ligand of FGFR1." (PMID 27974047, 2016). "Comparisons of brachyury and FGFR mRNA levels in paired lung tumor and adjacent normal tissues demonstrated that tumor tissues had significantly higher expressions of FGFR1, 3 and 4 and brachyury than normal tissues adjacent to tumor." (PMID 27893433, 2016).
tumor (continued). "Previous studies showed that FGFR inhibitors were effective to block tumor proliferation in a subset of NSCLC cell lines with FGFR1 amplification and led to significant tumor shrinkage." (PMID 27145277, 2016). "A total of 13/90 sqNSCLC samples (14.4%) were confirmed as FGFR1 gene amplified (defined as an FGFR1/CEN-8 gene probe ratio of ≥2 or cluster signals in ≥10% of tumour cells)." (PMID 26905262, 2016). "Alternatively, considering that N-cadherin drives tumor cell invasion/metastasis by associating with FGFR1 and preventing its endocytosis, we hypothesize that pro-N-cadherin promotes FGFR1 signaling more efficiently than does N-cadherin, resulting in increased tumor cell invasion." (PMID 27768598, 2016). "We have previously shown that a patient-derived tumour xenograft with FGFR1 amplification but low level FGFR1 protein expression was less sensitive to AZD4547 treatment than models with co-occuring FGFR1 amplification and high FGFR1 protein expression." (PMID 26905262, 2016). "We observed significant correlation of FGFR1 expression with high tumor pN, pT stages, large tumor size, and increased expression of several biomarkers (ER, Ki67, P63, CG, SYN and SOX2)." (PMID 26673008, 2016). "Further analysis disclosed that tumor tissues with FGFR1 immunoreactivity had significantly higher score of brachyury staining." (PMID 27893433, 2016). "Targeting FGFR1 alone resulted in rapid tumor regression, but tumors eventually recurred with latencies of 1 to 4 months." (PMID 26581390, 2015). "The phosphorylated epidermal growth factor receptor (EGFR) signaling pathway was upregulated in the recurrent tumors, and the combined inhibition of EGFR and FGFR1 signaling reduced the collagen-enriched stroma and significantly delayed tumor recurrence." (PMID 26581390, 2015). "Further studies are warranted to elucidate the mechanism of action for tumor growth inhibition in FGFR1-overexpressing HCC PDX models, and to confirm the genomic correlation of the drug sensitivity with overexpression of FGFR1 gene." (PMID 26062443, 2015). "Overall, these findings suggest that stroma remodeling during FGFR1 inhibitor treatment is important both for tumor dormancy and recurrence, and, furthermore, that recurrence can be delayed by inhibiting both FGFR1 and EGFR signaling." (PMID 26581390, 2015). "In a CRC tumour xenograft mouse model, combined therapy with a recombinant FGFR1 protein vaccine and low-dose gemcitabine suppressed tumour growth and antiangiogenesis was present." (PMID 26569228, 2015). "In the present study, the data revealed that the compounds Ad23 and Af23 suppressed the phosphorylation of FGFR1 in H460 tumor tissues, thereby inhibited the downstream phosphorylation of ERK and AKT, and reduced the expression of BCL-2, COX-2, and Cyclin D1." (PMID 25880284, 2015). "Until now, FGFR1 FISH on tumor biopsies has been the primary strategy utilized to recruit patients to molecularly enriched FGFR TKI trials." (PMID 27551478, 2015). "Accumulating evidence suggests that FGFR1 cascade plays a crucial role in tumor cell proliferation, angiogenesis, migration and survival." (PMID 25760077, 2015). "A recent study demonstrated that Debio 1347 (a selective orally available FGFR1–3 inhibitor) displayed preferential anti-tumor activity against cells with FGFR genetic alterations in a panel of 327 cancer cell lines and xenograft models." (PMID 26224133, 2015). "In one such study, vaccination with xenogeneic FGFR-1 plasmid DNA inhibited tumor endothelial cell proliferation and produced anti-cancer immunity in three murine tumor models." (PMID 26510973, 2015). "SNP array identified frequent shared copy number events in all three tumor regions including FGFR1 amplification at chromosome 8p11.23 and classical CDK4, HMGA2 and MDM2 amplification at chromosome 12q13-15 region and deletion of TP53BP1 at chromosome 15q15." (PMID 26643872, 2015).
tumor (continued). "Remarkably, FGFR1 amplification was also seen in dysplasia adjacent to tumor in 6 of 9 patients with FGFR1 amplified primary cancers." (PMID 26555375, 2015). "Using fluorescent in situ hybridization, high amplification was defined by an FGFR1/centromer 8 ratio is ≥ 2.0, or average number of FGFR1 signals/tumor cell nucleus ≥ 6.0, or percentage of tumor cells containing ≥ 15 FGFR1 signals or large cluster in ≥ 10%." (PMID 25537505, 2015). "Studies utilizing recombinant protein vaccines targeting FGFR-1 demonstrated significantly decreased tumor volume compared to controls, as well as decreased microvessel density in tumors without any observable overt toxicity." (PMID 26510973, 2015). "Further, CCND1 can enhance tumor progression, at least in part, by an increased level of transcription of FGFR1 and FGFR2 via E2F." (PMID 25596748, 2015). "Ad23 and Af23 exhibited a significant increased inhibitory effect on FGFR1 phosphorylation in H460 tumor xenografts than the vehicle control tumors." (PMID 25880284, 2015). "It will be important to determine which of the anti-apoptotic proteins in the BCL-2 family are the most important survival factors in FGFR1-overexpressing tumors to minimize adverse effects and increase tumor cell death." (PMID 27551478, 2015). "Exploratory biomarker analysis showed FGFR3, FGFR1, FGF-ligand and fibroblast growth factor receptor substrate 2 (FRS2) expression in the patient’s tumour, together with the presence of a germ-line mutation in the FGFR3 extracellular binding domain." (PMID 26497743, 2015). "Exploratory molecular analysis of the patient’s archival tumour sample included FGFR1 and FGFR3 protein expression by immunohistochemistry (IHC) and next-generation sequencing (NGS) analysis at Foundation Medicine." (PMID 26497743, 2015). "In a study of FGF-8 expression in OC, this cytokine was localized to tumor cells, whereas its receptors FGFR1, FGFR2, and FGFR4 were expressed by tumor cells, and to lesser extent, in stromal cells." (PMID 24860785, 2014). "Changes in fibroblast growth factor receptor type 1 (FGFR1) isoform expression were validated using PCR analyses of patient-derived tumor tissues versus matched normal tissues." (PMID 24618085, 2014). "Treatment Aea4 or Aea25 resulted in reduction in both tumor volume and weight, accompanied with a decrease in phosphorylated FGFR1 in tumor tissues of compound-treated mice." (PMID 24980830, 2014). "Not surprisingly, the patient-derived NSCLC xenograft models, L121 & L123 with FGFR1 gene amplification were insensitive to gefitinib treatment, likely due to a tumor-dependence on FGFR pathway signaling." (PMID 23842453, 2013). "Previous reports have demonstrated that combinatory inhibition of VEGFR-1 and FGFR-1 produced an enhanced suppression of tumor growth in different types of cancer." (PMID 23861711, 2013). "Although our results indicate that FGFR1 plays a less important role than FGFR3 in driving BC tumor cell proliferation, they also strongly suggest that FGFR1 plays crucial roles in invasion and metastasis." (PMID 23468956, 2013). "In conclusion, we have developed a quantitative real-time-PCR assay for quick and reliable determination of FGFR1 amplification in tumor specimens." (PMID 24255716, 2013). "In a mouse-xenografted CRC tumor, combined therapy with a recombinant FGFR1 protein vaccine and low-dose gemcitabine inhibited tumor growth and antiangiogenesis was present." (PMID 22701813, 2012). "ENMD-2076, a small-molecule kinase inhibitor with activity against the Aurora kinases A and B and several other tyrosine kinases, including VEGFR-2, cKit, and FGFR1, inhibited tumor growth in murine xenograft models of human CRC." (PMID 22701813, 2012). "Further studies will therefore be needed to elucidate the effect of FGFR1 amplification in epithelial cells on the tumor microenvironment and epithelial-stromal interactions." (PMID 22863309, 2012).